BACE1 (beta-secretase 1)
Diseases named in the same sentence as BACE1 in open-access papers (continued):
Sharing a sentence is not in itself a finding about the gene and the disease.
Cognitive impairment (continued). "For example, greater methylation levels at specific CpG sites of the BACE1 gene promoter were associated with lower Aβ load and higher tangle density in AD patients with dementia compared to subjects without cognitive impairment (NCI) or mild cognitive impairment (MCI)." (PMID 36359835, 2022). "Importantly, BACE1 inhibition rescued synaptic and cognitive impairment in animals following PM2.5 aspiration, which was further supported by the fact that overexpression of miR-574-5p robustly reduced BACE1 elevation and rescued synaptic and cognitive impairment." (PMID 28851397, 2017). "Serum levels of BDNF, BACE1, VEGF, GFAP, and IL-1β were evaluated through ELISA in patients with and without cognitive impairments." (PMID 40291844, 2025). "We examined the methylation level of twelve CpG sites a priori located in the promoter region of the bace-1 gene in cortical samples from 740 donors, of which 235 had no cognitive impairment (NCI), 175 had mild cognitive impairment (MCI) and 311 had AD." (PMID 27681803, 2016). "BACE1 levels are increased in AD brains and cerebrospinal fluid (CSF) and may lead to enhanced NRG1 secretion, but no study has assessed CSF NRG1 levels in AD and mild cognitive impairment (MCI) patients." (PMID 32690068, 2020). "Thus, we hypothesized that PM2.5 aspiration might promote BACE1- and γ-secretase- but not α-secretase-mediated cleavage of APP, leading to Aβ synthesis and accumulation and synaptic and cognitive impairment." (PMID 28851397, 2017).
amyloid (115 papers, 2005 to 2026). "Nrf2 mRNA is decreased in AD brains, and deletion of the Nrf2 gene causes increased BACE1 and Aβ production and worsened cognitive deficits in amyloid pathology mouse models." (PMID 41890066, 2026). "The pathological hallmark of AD, amyloid plaques derived from BACE1-cleaved APP, were significantly decreased in number and size of foci in the hippocampus and cortex of VIP@siBACE1-treated APP/PS1 mice." (PMID 38734698, 2024). "To investigate the role of BACE1 in oligodendrocytes, we conducted unbiased snRNA-Seq experiments to explore the underlying mechanism associated with amyloid plaque reduction." (PMID 39548583, 2024). "Hypomethylation of DSCAML1 gene enhancer is associated with an upregulation of BACE1 (beta-secretase 1) transcripts and an increase in amyloid plaques, neurofibrillary tangles, and cognitive decline." (PMID 36293477, 2022). "BACE1 is indispensable for the generation of Aβ since germline deletion of BACE1 gene abolishes Aβ deposition, preventing the subsequent development of amyloid-associated pathologies." (PMID 32917964, 2020). "In both of these models, the stroke-induced amyloid and tau deposition co-localized with AβPP cleavage enzyme, BACE1, and myelin-associated protein, NRG1 type III, both of which are critical for myelin repair." (PMID 30249297, 2018). "Together with our other genetic evidence, our BACE1-YFP transgenic results strongly support the conclusion that amyloid-associated BACE1 elevation occurs via a mechanism that is independent of eIF2α phosphorylation." (PMID 24992504, 2014). "Moreover, the involvement of BACE1 in the pathogenesis of amyloidosis associated with AD has been well established in the literature." (PMID 39056755, 2024). "In conclusion, we optimized a peptide using in silico tools to obtain a potent and competitive inhibitor of BACE-1, which is able to distribute and permeate the brain–blood barrier without causing any toxicity in mice and is useful for the treatment of amyloid-linked neurodegenerative diseases." (PMID 37397495, 2023). "To examine whether the reduced amyloidosis in the presence of ECH was caused by the reduction in APP metabolism through BACE1, we next examined the effect of ECH on the secretion of sAPPβ by Western blot." (PMID 33330477, 2020). "Indeed, alterations in cholesterol homeostasis facilitate amyloidosis and are associated with elevations in BACE1 levels and activity." (PMID 18005427, 2007). "Transduction of the Lenti-EGFP-SUMO1 vector to the hippocampus of APP/PS1 mice reduces the amount of Aβ and amyloid plaque, decreases the expression of sAPPβ and BACE1, but increases the expression of sAPPα." (PMID 41023583, 2025). "MAPT, APP, PSEN1, and BACE1 are key proteins involved in the pathological hallmarks of AD, namely neurofibrillary tangles and amyloid plaques." (PMID 41195325, 2025). "Accordingly, several studies showed that amyloid mice treated with chronic caffeine administration had lower hippocampal Aβ levels associated with a reduced presenilin 1 (PS1) and β‐secretase (BACE1) levels." (PMID 39099181, 2024). "Amyloid pathogenesis is initiated with abnormal cleavage of APP (integral plasma membrane protein) through β-secretases (BACE1) and γ-secretases." (PMID 39507054, 2024). "This study is the first to demonstrate that BACE1 levels increase early and in parallel with amyloid pathology in AD rat models." (PMID 37798744, 2023). "Together, these results demonstrate that sleep impairments correlate with amyloid plaque loads in 5xFAD mice, and both BACE1 inhibition and Bace1 deletion reduce plaque loads and rescues sleep impairments in this AD mouse model." (PMID 37536983, 2023). "The activity of BACE1 leads to the production of amyloid-beta, so BACE1 inhibitors have been developed to prevent the accumulation of amyloid-beta plaques in the brain of Alzheimer’s patients." (PMID 37444065, 2023).
amyloid (continued). "BACE-1 has the substrate amyloid precursor protein (APP) and generates amyloid plaques in the brain, causing several amyloid-linked neurodegenerative diseases." (PMID 37397495, 2023). "Immunostaining revealed that BACE1 accumulated in ring-like deposits, mirroring the distribution of amyloid plaques." (PMID 37798744, 2023). "As the BACE-1 positive dystrophic neurites are only present around amyloid plaques, this is consistent with overall reductions in amyloid plaque following removal of astrocyte apoE." (PMID 35109920, 2022). "SIRT3 activation in vivo also increased the levels of neprilysin, another Aβ degrading enzyme and decreased the levels of BACE1 which generates Aβ peptide suggesting SIRT3’s role in amyloid plaque reduction." (PMID 36396721, 2022). "BACE-1 is the enzyme degrading amyloid precursor protein (APP), leading to accumulation of amyloid plaques, another significant hallmark of neuropathological lesions in AD brain." (PMID 35161275, 2022). "Amyloidosis, which is implicated in cerebral amyloid angiopathy and AD, is reflected by aberrant cleavage of the full-length APP by BACE1 resulting in the production of soluble APP fragment and a membrane-bound CTF." (PMID 34027891, 2021). "This is the first report implicating the role of HIF-1α-BACE1 axis in morphine-mediated induction of astrocytic amyloidosis, leading, in turn, to neuroinflammation and release of the amyloid cargoes via ADEVs." (PMID 34527417, 2021). "For investigating the effects of pregabalin on amyloid pathology, dystrophic neurite formation, and BACE1 elevation in AD, we used the 5XFAD transgenic mouse model of amyloidosis." (PMID 34259145, 2021). "BACE1 elevation appears to correlate with amyloid pathology and accumulation of BACE1 is observed in normal and dystrophic presynaptic terminals surrounding the amyloid plaques in brains of AD mouse models and patients." (PMID 34349120, 2021). "The present study for the first time demonstrates the role of astrocytes in regulating morphine-mediated amyloidosis with the involvement of HIF-1α-BACE1 axis, ultimately resulting in neuroinflammation." (PMID 34527417, 2021). "BACE1 is elevated in the brains of A,D patients and mouse models of amyloidosis, specifically in presynaptic dystrophic axons and terminals around amyloid plaques." (PMID 34259145, 2021). "Gene silencing approaches confirmed the regulatory role of HIF-1α in BACE1 mediated amyloidosis leading to astrocyte activation and neuroinflammation." (PMID 34527417, 2021). "This would suggest the existence of a loop of amyloid production that will activate BACE1 to release more amyloid contributing to accelerate the dysregulation of BACE1 and the characteristic amyloidosis of AD." (PMID 33014268, 2020). "In particular, consumption of HFD increases amyloidosis-related factors such as beta-site amyloid beta precursor protein (APP) cleaving enzyme-1 (BACE-1), which elevates accumulation of Aβ plaques." (PMID 32397362, 2020). "Our data support that the mechanism involved in the increased BACE1 expression is the dysregulation of the phosphorylation of the eIF2α that would generate the amyloid burden in AD." (PMID 33014268, 2020). "In MCI and sporadic AD brain tissue, the levels and enzymatic activity of BACE1 are increased and localized to the surroundings of amyloid deposits." (PMID 31110178, 2019). "BACE-1 is the main β-secretase that is involved in the Aβ-generating process and plays a critical role in Aβ production and amyloidosis in the central nervous system." (PMID 31319549, 2019). "ADAM10, a competitor of BACE1, is not only promoting the expression of α-secretase that combats formation of amyloidosis, but also enhancing release of neuroprotective sAPPα." (PMID 29755351, 2018).
amyloid (continued). "In this context, it is important to emphasize that APPPS1 mice overexpress human APP with the Swedish mutation, which is more efficiently cleaved by BACE1 than wild type APP, which results in an aggressive model of early-onset amyloid pathology." (PMID 29327084, 2018). "Our results indicated that berberine was beneficial to decrease the generation of Aβ1-42 via inhibiting the enzymatic activity of BACE1, and disrupt the aggregation of Aβ1-42 into amyloid plaques." (PMID 30087614, 2018). "Although studied principally for its role in amyloidosis, BACE1 has multiple substrates other than APP, comprising transmembrane proteins involved in intercellular signalling." (PMID 27138913, 2016). "Our current findings therefore indicate that neuronal BACE1 induces global metabolic dysregulation along with brain inflammation and amyloidosis-related cognitive decline." (PMID 27138913, 2016). "Insights into the mechanism of BACE1 elevation in AD have come from analysis of the localization pattern of increased BACE1 in the brains of AD patients and transgenic mouse models of amyloid pathology." (PMID 26993139, 2016). "In both AD and APP transgenic mouse brains, BACE1 accumulates in swollen presynaptic dystrophic neurites that surround amyloid plaques in close proximity." (PMID 26993139, 2016). "The significant reductions of sAPPβ and its complementary membrane-bound C99 suggested a possible decrease of BACE-1 activity upon MT5-MMP deficiency, which would be consistent with lowered amyloidosis exhibited by TgMT5−/− mice." (PMID 28119565, 2016). "Here we show BACE1 expression in vascular endothelia, perivascular dystrophic neurites and meningeal cells at sites of vascular and leptomeningeal amyloidosis in aged human cerebrum." (PMID 25934480, 2015). "Briefly, in the cases of the amyloidosis group, BACE1 IR was increased at local sites against an overall neuropil-like background." (PMID 25934480, 2015). "The aspartic protease BACE1 is the initiator enzyme for the formation of Aβ, a major constituent of amyloid plaques." (PMID 25595891, 2015). "BACE1 protein levels were elevated in the lysates of the amyloidosis group (134.2 ± 19.2% of GADPH levels, mean ± SD) relative to control (95.0 ± 11.1%) (P = 0.021, n = 5, Paired t test, same test below)." (PMID 25934480, 2015). "Using immunofluorescence confocal microscopy, we likewise demonstrated that BACE1 immunoreactivity overlapped that of synaptophysin within many of the neuritic dystrophies adjacent to amyloid plaques." (PMID 23820808, 2013). "Next, we wanted to determine the type of vesicles within which BACE1 resides in dystrophic neurites that surround amyloid plaques." (PMID 23820808, 2013). "In the present study, we further demonstrated that inhibition of TNFα by thalidomide administration lowers BACE1 levels and activity and therefore ameliorates amyloid pathology." (PMID 23405115, 2013). "To gain insight into the second question, we performed immunofluorescence confocal and immunogold electron microscopy to determine where cerebral BACE1 accumulates in the 5XFAD transgenic mouse model of amyloid pathology." (PMID 23820808, 2013). "Of particular interest, elevations in BACE1 levels (∼2-fold) have been demonstrated to occur in brains of 5XFAD mice as amyloid pathology progresses." (PMID 20886088, 2010). "In some studies, reactive astrocytes around amyloid plaques appear to display BACE1 immunoreactivity in both Tg2576 Tg mice that develop amyloid pathology and human AD brain." (PMID 19415126, 2007). "Furthermore, DHA modifies BACE1 internalisation in the endosomes, reducing β-secretase activity and subsequently inhibiting amyloidosis, typical of AD." (PMID 40807232, 2025). "This could be attributed through BACE-1 activation, resulting in amyloid plaque development that promotes the pro-inflammatory reaction and creates a viscous cycle as seen in this study and documented before." (PMID 40381124, 2025).
amyloid (continued). "In addition, UCH-L1 influences β-Secretase 1 (BACE1) expression, resulting in the abnormal accumulation of amyloid-β plaques in brain parenchyma." (PMID 41009578, 2025). "A marked reduction in BACE-1 activity could slow or even prevent the progression of amyloid-related neurodegeneration, positioning SETL as a potential disease-modifying agent in AD treatment." (PMID 39598743, 2024). "In this context, BACE1 inhibition may provide a strategy to decrease the production of amyloid-β peptides, a major component of the amyloid plaques that accumulate in the brains of affected individuals." (PMID 39397872, 2024). "Instead of glucose, galactose was conjugated to the nanoparticle surface to allow efficient penetration of the BBB via glycemia-controlled GLUT1–mediated transport so that the encapsulated siRNA can be delivered to the brain to decrease BACE1 expression and reduce amyloid plaque levels." (PMID 37485250, 2023). "Furthermore, the fatty acid (FA) regulation of BACE1 has a potential effect on the upregulated activity of amyloidosis." (PMID 37744400, 2023). "Inhibition of BACE-1 in preclinical models has been shown to reduce Aβ production and amyloid plaque deposition, which may potentially delay the progression of AD." (PMID 37332343, 2023). "Besides consideration of LTP and behavioral performance, examination of the brains of HetCTR + TgCRND8 mice also revealed a significant decrease in several markers of AD pathology-amyloid plaque burden, BACE1, and soluble oligomeric Aβ." (PMID 34312771, 2021). "When combined with results from the in vitro study by Liu and colleagues, our in vivo results suggest one mechanism by which STAT3 inhibition attenuates amyloid pathogenesis and its associated neurovascular deficits is by attenuating APP processing through inhibition of BACE1 activity." (PMID 34911575, 2021). "To determine whether this potential regulatory role of STAT3 in BACE1 and γ-secretase expression underlies the observed impact of STAT3 inhibition on Aβ levels and amyloid pathogenesis, we examined BACE1 activity, levels of γ-secretase and soluble APPβ." (PMID 34911575, 2021). "Third, we identified two molecular mechanisms by which STAT3 inhibition may directly impact parenchymal and vascular amyloid pathogenesis—reduction in BACE1 activity and restoration of brain levels of LRP-1." (PMID 34911575, 2021). "Due to the correlation of amyloid plaque formation and AD, BACE1 has been closely studied." (PMID 34945753, 2021). "Therefore, activation of CREB and subsequent expression of autophagy/lysosomal protein is critical to the degradation of BACE1 and inhibition of amyloid pathological process in AD." (PMID 33682314, 2021). "We demonstrated, as expected, that in our hands female 5XFAD exhibited an increase in AD markers with age, including, an increase in APP and Bace1 expression, higher protein levels of BACE1 and sAPPβ, and higher number of amyloid plaques indicating the development of AD pathology in aged 5XFAD." (PMID 27013617, 2016). "We conclude that the amyloid-associated increase in BACE1 level is not caused by translational de-repression via eIF2α phosphorylation, but instead appears to involve a post-translational mechanism." (PMID 24992504, 2014). "Additionally, BACE1 levels are globally increased ∼1.5-fold in 5XFAD brain, with the vast majority of this BACE1 elevation being concentrated in dystrophic neurites that are in close proximity to amyloid plaques." (PMID 24992504, 2014). "By direct inhibition of eIF2α phosphorylation, here we definitively tested cause and effect relationships and conclusively show that reducing eIF2α phosphorylation does not decrease amyloid-associated BACE1 elevation in primary neuron cultures or 5XFAD mice." (PMID 24992504, 2014). "We conclude that amyloid-associated BACE1 elevation is not caused by translational de-repression via eIF2α phosphorylation, but instead appears to involve a post-translational mechanism." (PMID 24992504, 2014).